MIR583 (microRNA 583)
Synonyms: hsa-mir-583; MIRN583
Gene: MicroRNA gene on chromosome 5 (96,079,138 to 96,079,212, forward strand). Ensembl gene ENSG00000207578.
Gene Ontology:
Biological process: miRNA-mediated post-transcriptional gene silencing
Homologues: Orthologues: chimpanzee ptr-mir-583 (100% identical), macaque mml-mir-583 (96% identical).